IL6 (interleukin 6)
Diseases named in the same sentence as IL6 in open-access papers (continued):
Sharing a sentence is not in itself a finding about the gene and the disease.
ovarian carcinoma (continued). "Activation of STAT3 by microenvironmental IL-6 can also induce EMT in ovarian cancer cells." (PMID 30380628, 2018). "Similarly, CAFs were shown to be derived from mesenchymal stem cells in ovarian cancer and supported tumor growth through the secretion of the paracrine factor IL-6." (PMID 30380628, 2018). "Concerning ovarian cancers, we have shown that IL-6 could be overexpressed by the ovarian adenocarcinoma cells themselves or by cells within their microenvironment." (PMID 29930760, 2018). "Moreover, high serum levels of proinflammatory cytokines such as IL-6 (or IL-8) were noted in the ascites of epithelial ovarian cancer patients presenting with a poor prognosis." (PMID 29930760, 2018). "Interestingly, ascites from ovarian cancer patients can also promote monocytes to differentiate into M2 macrophages; further analysis found that the ascites contained a high concentration of IL-6." (PMID 29707119, 2018). "To further clarify the role of IL-6 and the secreted factors, we designed an experimental model in which mesenchymal cells extracted from neoplastic ascites interact, in a serum-free environment, with ovarian cancer cells exclusively through secreted factors." (PMID 29455640, 2018). "DHMEQ was found to inhibit the production of IL-6 and IL-8 in epithelial ovarian cancer cell lines." (PMID 29510517, 2018). "In epithelial ovarian cancer patients, increase of plasma IL-6, and IL-8 were observed." (PMID 29510517, 2018). "Thus, the presence of LPA in the stroma can limit the autophagy compliance in ovarian cancer cell through a direct autocrine action or via indirect stimulation of IL‐6 by CAFs." (PMID 28926101, 2018). "Synthesis of tumor-promoting factors including CCL2 and IL-6 is minimized in TAMs and ovarian cancer cells upon treatment by Trabectedin (Yondelis), an agent that originates from the tunicate Ecteinascidia turbinate, binds DNA minor grooves and inhibits monocyte differentiation into macrophage." (PMID 28929459, 2018). "Because secreted IL-6 contributes to chemoresistant cancer stem cells by inducing aldehyde dehydrogenase (ALDH1A1) we performed a survival assay with conditioned media (CM) from ovarian cancer cells treated for 24 hours with either PNA3 or control PNA." (PMID 28420874, 2017). "Moreover, the inhibition of thrombopoietin and IL-6 expression abrogated thrombocytosis in tumor-bearing mice and significantly enhanced the therapeutic efficacy of paclitaxel in mouse models of epithelial ovarian cancer." (PMID 28903428, 2017). "Furthermore, several studies have demonstrated highly significant associations between the ascites levels of various cytokines and the relapse-free survival (RFS) or overall survival (OS) of ovarian cancer patients, for example, TGFβ, IL-6, IL-10, and LIF." (PMID 28275576, 2017). "In this study, an association between ascites pro-inflammatory cytokine IL-6 and salivary cortisol was observed; indicating night concentration may be an efficient biomarker for measuring HPA function in ovarian cancer population." (PMID 28512552, 2017). "Importantly, CA125 and HE4 are present in this quadrant, as well as other proteins that have been reported to be elevated in the sera of women with ovarian cancer, such as interleukin-6, midkine, folate receptor-alpha, KLK6, and hK11." (PMID 29051715, 2017). "In addition, the size and efficiency of tumor formation were dependent on IL-6 secretion in human ovarian cancer cells." (PMID 29259311, 2017). "A recent published study of ovarian cancer proposed that thrombocytosis might be a paraneoplastic syndrome that indicates itself through tumor-derived IL-6, which activates thrombopoiesis, resulting in thrombocytosis and tumor progression." (PMID 28212582, 2017). "IL-6 is a factor known to be involved in the initiation and progression of ovarian cancer." (PMID 28859117, 2017).
ovarian carcinoma (continued). "IL-6 released by TAMs promotes the adhesion, invasion, and proliferation of ovarian cancer cells, which might be mediated in part by an increase of MMP expression by ovarian cancer cells." (PMID 28275576, 2017). "Moreover, VEGF, interleukin-8 (IL-8) and interleukin-6– (IL-6) have been identified to play important roles in ovarian cancer angiogenesis." (PMID 29088837, 2017). "In addition to VEGF, IL-8 and IL-6, there are also many other proangiogenic factors that participate in ovarian cancer angiogenesis." (PMID 29088837, 2017). "IL-6/IL-6R signaling was proved to play a significant role in the progression of ovarian cancer." (PMID 28821817, 2017). "SphK blockage suppressed VEGF, IL-8 and IL-6 secretion in ovarian cancer cells." (PMID 29088837, 2017). "Here we found that IL-6 further promotes production of MMP-9 by ovarian cancer cells." (PMID 28859117, 2017). "Additionally, IL-6-targeted therapy has been found to be capable benefiting the treatment of ovarian cancer." (PMID 26817451, 2016). "IL-6 monoclonal antibodies, Siltuximab and Tocilizumab, which bind to the soluble form of the IL-6 receptor are available for trial and currently under assessment in ovarian cancer." (PMID 27170998, 2016). "From relative comparison, we found IL-6 expression only in ovarian cancer patient derived ascites." (PMID 27825119, 2016). "Based on these results, we reasoned that the IL-6/STAT3 pathway might be important for regulating Par3 function in certain types of ovarian cancer cells." (PMID 27855669, 2016). "At least, it seems that IL-6 accumulation in ascites induces skewing of monocytes into TAMs and differentiated TAMs further produce IL-6, which leads to the invasion, proliferation and angiogenesis of ovarian cancer cells." (PMID 25658637, 2015). "Exogenous treatment of IL-6 robustly induced cell invasion of ovarian cancer cells in a dose dependent manner (IL-6 100ng/ml; SKOV3ip1, 4.27 ± 0.53 fold, RMG-1, 2.99 ± 0.46 fold), whereas the induction was almost completely inhibited by the pretreatment with anti-IL-6R antibody." (PMID 25658637, 2015). "It appears that antagonizing IL-6/IL-6R signaling may have therapeutic activity in patients with ovarian cancer through the inhibition of a tumor-promoting cytokine network." (PMID 25658637, 2015). "Similarly, siRNA knockdown of IL-6 inhibited IDO expression in SKOV3 ovarian cancer cells and reduced the ability of tumor cells to suppress T cell responses in mixed lymphocyte reactions." (PMID 26343197, 2015). "Exogenous treatment of IL-6 also significantly enhanced the proliferation of both ovarian cancer cells in a dose dependent manner (IL-6 100ng/ml; SKOV3ip1, 1.60 ± 0.29 fold, RMG-1, 1.64 ± 0.39 fold) and the pretreatment of anti-IL-6R antibody almost abolished these enhancements." (PMID 25658637, 2015). "Since IL-6/IL-6R signaling contributed to ovarian cancerprogression in a paracrine way, we considered that inflammatory microenvironments surrounding ovarian cancers may constitute cytokine-rich environments, especially by producing IL-6." (PMID 25658637, 2015). "There is increasing evidence that IL-6/IL-6R signaling may play a significant role in the progression of various cancers, including ovarian carcinomas." (PMID 25658637, 2015). "The implication of IL-6 in the pathogenesis of epithelial ovarian cancer (EOC) is well documented." (PMID 26282935, 2015). "The majority (87.8%) of CD11b+CD14+ cells were CD-68, a surface marker of macrophages, and CD-206, a surface marker of positive M2-polarized macrophages, suggesting that IL-6 producing cells in ovarian cancer ascites are predominantly M2-polarized macrophages, TAMs." (PMID 25658637, 2015). "Of 94 patients, 39 (41.4%) showed “high” IL-6 expression, including 13 of 34 serous (38.2%), 8 of 16 mucinous (50.0%), 5 of 11 endometrioid (45.5%), 11 of 20 clear cell (55.0%) and 2 of 13 other (15.4%) ovarian carcinomas." (PMID 25658637, 2015).
ovarian carcinoma (continued). "Previous studies have indicated that PI3K/Akt is a crucial event in P2Y13 signaling, and that Gi-mediated PI3K activation phosphorylates downstream Akt and subsequently induces IL-6 production in ovarian cancer cells; these results strongly support our conclusions." (PMID 26030257, 2015). "Therefore, we were encouraged to investigate the clinical values of IL-6 and IL-6R in ovarian cancer tissues using the tissue microarrays (TMAs) we constructed and the corresponding clinical data." (PMID 25658637, 2015). "IL-6 increases the metastasis of ovarian cancer cells by effecting their migration and attachment." (PMID 24683359, 2014). "Paclitaxel up-regulates IL-8 and IL-6 expression in human lung and ovarian carcinoma cell lines." (PMID 25511260, 2014). "IL-6 is considered to be involved in host immune responses to types of ovarian cancer." (PMID 24527095, 2014). "This property of NTZ could be particularly relevant in ovarian carcinoma where IL-6 is often overexpressed in many paclitaxel-resistant ovarian cancer cells." (PMID 24202339, 2013). "Thus cytokine inhibitors interrupting the cross-talk between OCC and MSC such as IL6 should be investigated as a therapeutic approach in ovarian cancer." (PMID 23369187, 2013). "Thus a model was proposed according to which ovarian cancer tumor cells produce IL-6 which stimulates the liver to produce thrombopoietin, finally resulting in increased thrombopoiesis through stimulation of megakaryocyte progenitors in the bone marrow." (PMID 23864954, 2013). "Since we observed that DIM can suppress IL-6-induced activation of STAT3 in ovarian cancer cells, we hypothesized that DIM mediated inhibition of STAT3 is in fact by inhibition of IL-6." (PMID 22280969, 2012). "IL-6 is a pro-inflammatory cytokine highly expressed in the tumor context of type-2 ovarian cancers and in ascitic fluid, and its level correlates with poor prognosis in ovarian cancer patients." (PMID 22974323, 2012). "Furthermore, DIM treatment dramatically reduced the secretion of IL-6 not only in ovarian cancer cells but also in tumors." (PMID 22280969, 2012). "The cytokines, including IL-4 (p = 0.017) and TNF-α (p = 0.046), significantly decreased while others such as TGF-β (p = 0.013), IL-6 (p = 0.016), and IL-10 (p = 0.018) were elevated in ascites of ovarian cancer patients, when the disease progressed to advanced stages." (PMID 23082146, 2012). "Another study demonstrated that anaemia in advanced stages of ovarian cancer may be related to the levels of IL-6." (PMID 22577583, 2012). "Overexpression of IL6 has been detected in the majority of ovarian cancers." (PMID 22481926, 2012). "High levels of circulating IL-6 were observed in ovarian cancer patients." (PMID 22280969, 2012). "We therefore measured IL-6 secretion by ovarian cancer cells using a commercial ELISA kit." (PMID 22280969, 2012). "In the present study, we provide evidence that DIM induces apoptosis in ovarian cancer cells by blocking the activation of STAT3 and its downstream effector molecules, while IL-6 treatment or overexpression of STAT3 significantly protects ovarian cancer cells from DIM-induced apoptosis." (PMID 22280969, 2012). "Based on the observation that ovarian cancer ascites may affect tumor progression and reported elevated levels of IL-6 and IL-8 in ascites, we hypothesize that these cytokines might affect the clinical progression of patients with ovarian cancer." (PMID 21619709, 2011). "Despite these data, the biological relevance of high levels of IL-6 and IL-8 in ovarian cancer ascites remains mostly unknown." (PMID 21619709, 2011). "In ovarian cancer, IL-6 is thought to be involved in host immune responses to the disease." (PMID 21619709, 2011). "Because IL-6 has been shown to be involved in tumor angiogenesis in ovarian cancer, IL-6 may be important in promoting the formation of ascites as well as the progression of ovarian cancer." (PMID 21619709, 2011).
ovarian carcinoma (continued). "IL-6 has also been demonstrated to be involved in autocrine growth of ovarian cancer cells." (PMID 21619709, 2011). "However, levels of IL-6 secreted by mesothelial cells are 600-fold higher than those secreted by ovarian cancer cells." (PMID 21619709, 2011). "Consistent with this fact, neutralising anti-IL6R partially inhibited EGF-induced migration in OVCA 433 cells, suggesting that EGF-induced migratory phenotype is dependent to a certain extent on the EGF-induced expression of IL-6 in certain ovarian cancer cells." (PMID 19088723, 2009). "To determine if mRNA increase in IL-6R expression in response to EGF treatment has any affect on the production of IL-6 in ovarian cancer cell lines, we used IL-6 sandwich ELISA to quantify the amount of IL-6 secreted by OVCA 433 and SKOV3 cell lines in response to EGF." (PMID 19088723, 2009). "The expression of IL-6 was significantly elevated in both ovarian cancer cell lines." (PMID 19088723, 2009). "Both OVCA 433 and SKOV3 cell lines produced IL-6 endogenously but, in the presence of EGF, the production of IL-6 was increased (P<0.05) in the serum-free medium of both ovarian cancer cell lines, consistent with the mRNA enhancement of IL-6 and IL-6Rα on the cells." (PMID 19088723, 2009). "High levels of IL-6 were found in 50% of 114 patients with primary ovarian cancer." (PMID 7841052, 1995). "For instance, sRNAs derived from Fusobacterium nucleatum may suppress the transcription of tumor suppressor genes such as BRCA1 while promoting the epigenetic activation of pro-inflammatory genes like IL-6, thereby accelerating the progression of ovarian cancer." (PMID 40732683, 2025). "Additionally, exosomes isolated by differential centrifugation from ovarian cancer patients' amniotic fluid or ascites activate Toll-like receptor to boost interleukin-6 (IL-6) production in monocytes and activate the STAT3 pathway in tumor cells, stromal cells, and immune cells." (PMID 38796525, 2024). "In addition, BTZ increased the IL-8 level in ovarian cancer cells and in human monocytes and macrophages in vitro, thereby also inhibiting the expression of IL-6 and IL-1, which may explain why its expression was increased in our study." (PMID 38835345, 2024). "Finally, emerging data from several groups indicate that IL-6 signalling may be critical to EMT in epithelial ovarian cancer." (PMID 38689325, 2024). "Furthermore, elevated level of serum cytokines IL-2, IL-5, IL-6, IL-10, and TNF-α in ovarian cancer patients, might be associated with ovarian cancer progression." (PMID 37322531, 2023). "Therefore, further studies on the effect of IL-6 blockers in ovarian cancer are needed and elucidating the correlation between IL-6 activated STAT3 phosphorylation and FoxO3a may suggest and exciting new therapeutic directions." (PMID 37047012, 2023). "By using three ovarian cancer cell lines with different genetic background in 2D and 3D models, the latter mimicking the growth of peritoneal metastases, we show that RV keeps the cancer cells in a dormant-like quiescent state contrasting the IL-6 growth-promoting activity." (PMID 35565270, 2022). "We found that CAFs from malignant fluids of ovarian cancer receive a specific signaling pattern from cancer cells, mainly composed of ligands associated with neovascularization processes, differentiation pathway, EGFR tyrosine kinase inhibitor resistance, and IL-6/JAK/STAT3 signaling." (PMID 36352420, 2022). "A study that followed ovarian cancer patients prior to primary treatment to 1 year post-treatment, found that patients showed significant reductions in nocturnal salivary cortisol secretion and plasma IL-6 and a more normalized diurnal cortisol rhythm at 6 months with changes maintained at 1 year." (PMID 36387255, 2022).
ovarian carcinoma (continued). "The authors of this preclinical study demonstrated that high levels of IL-6 contained in the ADSC-conditioned medium activated the STAT3 pathway, which is linked with the promotion of tumor growth and invasion and is responsible for the increase in autophagy in ovarian cancer cells." (PMID 34440886, 2021). "Notably, in ovarian cancer, in vitro studies have illustrated how IL-6 could induce, through STAT-3, the upregulation of HIF as well as overexpression of hexokinase and associated glycolytic pathway." (PMID 33550983, 2021). "Thus, blocking the activation of JAK2 and STAT3 via inhibitors, siRNAs, or neutralizing IL-6 could suppress ovarian cancer cell migratory capacity, making them possible targets for future therapeutic approaches." (PMID 34440886, 2021). "In addition, IL-6 promoted the enrichment of ovarian cancer stem cells after platinum treatment." (PMID 34369236, 2021). "Indeed, in ovarian cancer, the constitutive production of IL-6 by cancer cells has been strongly demonstrated, as wells as IL-6 ability to promote tumor growth and progression through autocrine and paracrine actions and to cause specific immune and metabolic alteration that impact prognosis." (PMID 33550983, 2021). "Notably, the expression of AhR has been shown to mediate the IL-6 expression in ovarian cancer, and Kyn derived from Trp metabolism could efficiently promote the activation of AhR signals in a diverse of tumor cells." (PMID 34657635, 2021). "In the TME, IL6 also regulates immune cell transformation from monocytes to a suppressive M2 phenotype, thereby promoting the proliferation and metastasis of various cancers, including lung, breast, hepatocellular, prostate, colorectal, renal cell, cervical, and ovarian cancers." (PMID 34141615, 2021). "Because tumor‐derived interleukin (IL)‐6 increases hepatic thrombopoietin synthesis and platelet production, as well as increases thrombotic events in patients with ovarian cancer, it has been suggested that interfering with the IL‐6‐thrombopoietin pathway may reduce VTE events." (PMID 33638309, 2021). "IL-6 is one of the major immunoregulatory cytokines present in the ovarian cancer microenvironment while IL-6 antagonists may exert therapeutic effects against ovarian cancer." (PMID 33550983, 2021). "Even broader roles for NAC1 and BCL6 might exist in ovarian cancer, as ingenuity pathway analysis has revealed the upregulation of IL-17, IL-8, and IL-6 signaling pathways, which were reported to be correlated with novel functions in driving tumor growth and stemness." (PMID 32412910, 2020). "In contrast, excessive levels of circulating IL-6 are observed in advanced ovarian cancers and this may be contributed by either tumour cells or peritoneal mesothelial cells, both of which are major contributors to IL-6 production within the tumour microenvironment." (PMID 32042020, 2020). "Altogether, above these results proved that p-STAT3/NF-kB was a crucial axis in the development of ovarian cancer for increasing the expression of IL-6 and VEGF which created a feedback loop to activate p-STAT3/NF-kB axis as a cascade amplification method, and At-EE could restrain this phenomenon." (PMID 32190078, 2020). "Moreover, it has been described that IL6 acts as a pro-metastatic factor in ovarian cancer cells." (PMID 32326210, 2020). "Likewise NO has been shown to suppress IL-6-induced STAT3 activation in ovarian cancer cells." (PMID 29800237, 2018). "Thus, secreted IL-6- could act in an autocrine manner on ovarian cancer cell surface receptors as well as activating the PI3-kinases." (PMID 29930760, 2018). "Also, several other components of IL6 signaling were affected, further supporting previous observations on its importance in malignant transformation and development of drug resistance in ovarian cancer." (PMID 28473707, 2017).